IL4 (interleukin 4)
Diseases named in the same sentence as IL4 in open-access papers (continued):
Sharing a sentence is not in itself a finding about the gene and the disease.
tumor (continued). "IL-4 is an anti-inflammatory cytokine, and we detected a significant increase in serum IL-4 in NSCLC patients, which may contribute to the survival, growth, and metastasis of tumor cells." (PMID 40308600, 2025). "The M2 phenotypes are, on the other hand, stimulated by IL-4 and IL-13 to produce and secrete growth factors such as VEGF and TGF-β, MMPs and other cytokines such as IL-10, IL-13 and IL-4, and in that way contribute to increased proliferation of tumor cells and angiogenesis in the TME." (PMID 40376304, 2025). "Macrophages also migrate to the tumor site, where tumor cells are responsible for a switch in macrophage phenotype, favoring a pro-invasive and immunosuppressive M2 state via the release of immunosuppressive factors, such as CSF-1, CCL2, IL-4, IL-6, IL-10, and TGF-β." (PMID 41373591, 2025). "This process involves the secretion of inflammatory cytokines (such as IL-4 and IL-10) and vascular endothelial growth factor (VEGF), which activate relevant signaling pathways, such as NF-kB, thereby promoting the formation of blood vessels and the survival of tumor cells." (PMID 40098971, 2025). "In addition to CSF1 and IL-4-mediated TAM reprogramming, the chemokine CXCL16 released from tumor cells has also been shown to bind to CXCR6 on microglia cells and drive them toward a pro-tumor phenotype." (PMID 38254796, 2024). "In order to confirm that it is high levels of IL-4 that inhibit the efficacy of immunotherapy, rather than high proliferation of tumor cells after drug resistance and excessive production of IL-4, we verified in animal models that IL-4 can inhibit the efficacy of mouse PD-1 antibody." (PMID 39003253, 2024). "Interestingly, prolonged co-culture with tumor cells for three weeks resulted in spontaneous M2 polarization of macrophages without the need for IL-4 treatment." (PMID 37686542, 2023). "Csf1, but not Csf2 or Il4, was highly expressed in tumors compared with tumor-distant liver tissues, implying that enhanced local production of M-CSF may stimulate KC mobilization and proliferation." (PMID 36821387, 2023). "Anti‐tumour effects were assessed by measuring pathologic complete response (pCR), survival analysis, immunohistochemistry for E‐cadherin, VEGF, MMP9, MMP2 and Ki‐67, serum measurement of IFNγ and IL‐4, and gene expression analysis of CD105, VEGFa, VEGFR2 and COX2." (PMID 37581480, 2023). "Moreover, IL4 and IL13 released by the CSCs also bring about the pro-tumor state of macrophages." (PMID 38035101, 2023). "To understand whether the macrophage mode of activation changes the effects they exert on the tumor cells, we activated RAW 264.7 macrophages for 24 h as M0 (no treatment), M1 (incubation with 100 U/mL IFNγ and 100 ng/mL LPS) or M2 (incubation with IL-4 and IL-13, 20 ng/mL each)." (PMID 36979746, 2023). "Our studies indicate that the recipient T cell IL-4 and Th2 regulatory loop and TGF-β production promote recipient T cell survival, mimicking mixed chimerism, and regulate GVHD after myeloablative preparation (TBI) and also prevent tumor growth by preserving the graft-versus-tumor effect." (PMID 37294277, 2023). "The GAS6/AXL axis regulates many tumor immune-related biomolecules, e.g., major histocompatibility complex I (MHC-I) and programmed death ligand-1 (PD-L1) in tumor cells, and the levels of secreted anti-inflammatory cytokines such as IL-4, CCL3-5 and granulocyte colony-stimulating factor (G-CSF)." (PMID 37265798, 2023). "Joint decrease in IL-2 and IL-4 could be inducing a decrease in certain Tregs function after NAC, which would explain the stromal and tumor decrease in FoxP3 reported here, as well as the significant association between post-NAC expression of IL-10 and IL-17 and failure to obtain pCR." (PMID 37104271, 2023).
tumor (continued). "Additionally, tumor-derived EVs containing lnc-TALC can promote the M2 polarization of microglia by increasing the expression of Arginine-1 (Arg-1) and CD163, as well as M2-related cytokines (TGF-β, IL-4 and IL-10), via p38 of the MAPK pathway activation." (PMID 37175226, 2023). "Additionally, Ad5f35 transduced macrophages did not differentiate into M2 macrophages when stimulated with IL-4, IL-10, IL-13 or a tumor-conditioned medium." (PMID 37510993, 2023). "The results of the in vivo study showed that SPION@Cs-PTX-PEG-FA significantly decreased tumor size compared to free PTX and control samples (P < 0.05), leading to longer survival, significantly increased splenocyte proliferation and IFN-γ level, and significantly decreased the level of IL-4." (PMID 36823237, 2023). "Flow cytometric analysis of intracellular cytokine production revealed a greatly increased accumulation of CD4+ and CD8+ IL-4+ T cells in the draining lymph nodes of LY2-injected HNSCC tumor-bearing mice compared to non-tumor-bearing mice, but not in the MOC2 HNSCC model." (PMID 37444444, 2023). "Interestingly, IL-4 expression in the IL-5 KO mice was similar to that of WT mice, but IFN-γ levels were almost three times higher in the IL-5 KO mice, which showed how Th1 suppression favored tumor metastasis." (PMID 37587450, 2023). "GHCer could be transferred from cancer cells into non-tumor cells located in the tumor microenvironment, such as endothelial cells, promoting angiogenesis, as well as into T cells, inhibiting IL-2, interferon-γ, and IL-4 secretion, promoting immunosuppression." (PMID 38203654, 2023). "In addition, this study also demonstrated that low expression of SHP-2 further stimulated IL-4-induced M2 macrophages to produce IL-10 and Arginase-1, which in turn further aggravated macrophage M2 polarization and ultimately promoted CRC tumor invasion and metastasis." (PMID 36776333, 2023). "Moreover, studies have shown that molecules including Il-4 and CD163 secreted by M2-polarized macrophages can induce pathological angiogenesis, which may increase the blood supply to the tumor microenvironment." (PMID 36945046, 2023). "In the comparison to the M0 control, all interventions (LPS, IL-4, tumor supernatant, and WGP) upregulated Dectin-1 and the elevated Dectin-1 from IL-4 and tumor supernatant induction, but not LPS, could be enhanced by WGP." (PMID 36142859, 2022). "However, in advanced tumors, anti-inflammatory mediators released in the TME, such as CSF-1, CCL2, IL13, IL4, IL10, and prostaglandin E2 (PGE2), can revert the anti-tumor program and favor a switch of TAM into an M2 phenotype with pro-tumor and immunosuppressive functions." (PMID 35163420, 2022). "Moreover, tumor-recruited Lyve-1+ lymphatic progenitors in vivo expressed all Th2 receptors as well as corresponding ligands, including IL-4 and IL-13, which were absent in BM cells." (PMID 35442077, 2022). "Thus, IL4 signaling was not required for macrophage-enhanced tumor cell transendothelial migration in this assay, but IL4 potentiated the macrophage activity." (PMID 36077870, 2022). "The proinflammatory cytokines, IFN-γ, IL-4, IL-6 and IL-1β, promote MDSC expansion and activation and generate reactive oxygen species (ROS) and nitric oxide (NO), which contribute to immunosuppression and reduced T cell function within the tumor microenvironment." (PMID 35655772, 2022). "Thus, IL4 signaling maintained the stability of MAM–tumor cell interactions but not their initial interactions with monocytes." (PMID 36077870, 2022). "Ddx5 was increased in the whole skin lesions of MC903- or IMQ-treated Cd93–/– mice compared with their wild-type counterparts, along with fewer plaques on the ears or dorsal skin and reduced expression of Il4, Il13, Ccl11, Ccl17 and Ccl22 or Cxcl1, Cxcl2, Ccl20, Il23, Il17a and Il36γ." (PMID 36271146, 2022).
tumor (continued). "The polysaccharides could activate macrophages, T-lymphocytes, B-lymphocytes, natural killer cells, and cytokines that are closely related to the killing of the tumor, such as tumor necrosis factor (TNF-α), interferon (IFN-γ), and interleukins (IL-2, IL-4, IL-6, and IL-12)." (PMID 35295918, 2022). "More importantly, tumour clearance was reduced in mice lacking the Th2 cytokines IL-4 and IL-5." (PMID 36261459, 2022). "Interestingly, microglia isolated from HRasV12+ larval brains showed increased expression levels of il4 and il11 (not shown), suggesting the generation of an anti‐inflammatory state during tumor initiating stages." (PMID 35194846, 2022). "Strikingly, supernatant of Phd2+/– BMDMs stimulated with LPS or IL-4 significantly increased tumor cell viability of CMT-93 cells compared with treatment with supernatant of WT BMDMs stimulated with LPS or IL-4, indicating that Phd2+/– macrophages can promote tumor growth in vitro." (PMID 36509284, 2022). "Because our analyses of tumor-bearing mice treated with cGAMP also revealed an increased frequency of IL-9-producing CD4 T cells in the tumor microenvironment, we finally evaluated the contribution of other CD4 T cell-derived cytokines (IL-9, IL-17, and IL-4) to the anticancer effects of cGAMP." (PMID 35091453, 2022). "For illustration, in the tumor microenvironment, the M1 macrophages could be activated by interferon (IFN)-γ with lipopolysaccharides and M2 macrophages could be activated by interleukin-4, which were involved in the tumor progression and metabolic reprogramming." (PMID 36046784, 2022). "Additionally, tumor volume and mass; thymus index; spleen index; the serum cytokines IL-2, IL-4 and TNF-α; IFN-ɤ levels and tumor histopathology could be detected as detection indicators." (PMID 36080446, 2022). "The expansion of fibroblasts is seen in the early tumour stage where CAFs act as “tumour suppressors”, producing gap junctions which subsequently turn CAFs into “tumour promoters”, as activated by tumour-secreted factors such as PDGF, FAP, interleukin-4, interleukin-6 and prostaglandin E (PGE)." (PMID 36101394, 2022). "M2 MΦs induce tumour progression by driving tumour proliferation directly or indirectly by dampening T-cell functions through the secretion of cytokines and factors such as TGF-β, IL-10, IL-4, vascular epidermal growth factor (VEGF) and matrix metalloproteases (MMPs)." (PMID 35454848, 2022). "Moreover, our results demonstrated that the frequencies of IL-10+CD8+ and IL-4+CD8+ T cells had positive correlations with the tumor size, however the latter was not statistically significant (R = 0.4, P = 0.013, R = 0.3, P = 0.098, respectively)." (PMID 36376825, 2022). "IL-4 could increase the expression of PD-L1 through JAK-STAT pathway in both TAM and tumor cells." (PMID 35996149, 2022). "Furthermore, we have shown that peritoneal macrophages that originate from either aged (26 months) C57BL/6J female mice or Balb/c female mice (18 months) stimulated with tumor-derived factors increased production of TGF-β1 and IL-4, relative to macrophages from young mice." (PMID 33441138, 2021). "While not identical, the M(IL4) and other AAMs share some similarities with myeloid-derived suppressor cells (MDSC) and tumor-associated macrophages (TAMs), raising the possibility that M(IL4)s could promote or exaggerate tumorigenesis." (PMID 34691050, 2021). "IL-4 induces immune deviation from TH1 to TH2 responses, which prevents tumor rejection; IL-10 suppresses the anti-tumor immunity and contributes to tumor immune escape and IL-13 compromises the anti-tumor response by inhibiting IFN-γ secretion and CD8+ T lymphocyte activity." (PMID 35047997, 2021).
tumor (continued). "Subsequently, transfection of tumor cells with genes coding for cytokines that promote antigen presentation (discussed later), activate T cells and APC or induce costimulatory molecules (IFNγ, IL-2, IL-4, IL-7, GM-CSF) were shown to increase tumor immunogenicity and elicit antitumor immunity." (PMID 33671123, 2021). "However, there were no changes in the level of the Th2 cytokine IL‐4 in any of the groups, suggesting that immunization with SyBV primes a tEV‐driven tumour‐specific Th1 immune response." (PMID 34262675, 2021). "Moreover, combination treatment showed downregulation of the expression of inflammation-related genes that are involved in tumor inflammation, such as Gremlin (GREM1), IL-1β, IL-4, NF-κB, and prostaglandin-endoperoxide synthase 2 (PTGS2), tumor nitric oxide level." (PMID 34959865, 2021). "Moreover, IL-4, through activation of NFAT and STAT6 transcription factors, induces the expression of IGF-1 in TAMs, which signals neighboring tumor cells to activate the PI3K pathway to promote cell proliferation and tumor expansion." (PMID 34949203, 2021). "The results revealed that transfer of DXM/lactoferrin PMN-MDSCs, Con PMN-MDSCs, and tumor PMN-MDSCs transfer and treatment with DXM decreased the bronchoalveolar lavage fluid (BALF) cell count, eosinophil granulocyte percentage, pathological grade, and IL-4 concentration." (PMID 33637832, 2021). "However, IL-4 and IL-10, defined as anti-inflammatory cytokines in DII calculation, could pose both anti-cancer and pro-cancer actions in the tumor microenvironment depending on the specific molecular and cellular context." (PMID 34684331, 2021). "For example, we have previously published that in response to tumor-derived factors elderly-derived peritoneal macrophages from female C57BL/6J mice (aged 24–28 months) and Balb/c mice (18 months) secrete increased levels of TGF-β1 and IL-4 compared to young mice." (PMID 33441138, 2021). "In addition to tumor cells, these cells facilitate tumor growth and proliferation by producing growth factors, local cytokines, and chemokines in solid tumors, including VEGF and IL-4, IL-10, and TGFβ." (PMID 33494834, 2021). "In contrast, upon exposure to IL-4, IL-10, and IL-13, transforming growth factor beta 1 (TGFβ1), and prostaglandin E2 (PGE2), macrophages can undergo M2 activation, which is characterized by tissue repair, matrix remodeling, and tumor promotion, and mirrors those of Th2 responses." (PMID 34300195, 2021). "In conclusion, Acly is crucial for IL-4-induced mouse macrophage activation, and myeloid-specific KO of Acly slightly affects tumor immune composition and TAM phenotype without affecting tumor growth, suggesting that cancer therapies targeting Acly do not negatively affect TAMs." (PMID 34205266, 2021). "Cytokines released from tumor-residing cells including tumor cell–derived IL-4, IL-10, CCL2, CCL3, CCL4, and CSF1; Treg-derived IL-10; B cell–produced immunoglobulins; Th2-derived IL-4 and IL-13; and MSC-derived MFG-E8 promote the polarization into a protumor phenotype." (PMID 31256327, 2020). "Furthermore, M-CSF, IL-4, IL10, and TGF-β secreted by tumor cells can trigger the M2 program." (PMID 32487125, 2020). "Moreover, as IL‐4 contributes to tumour growth, metastasis and chemotherapy resistance, this fact indicates that IL‐4 might be crucial for YY2‐mediated tumour suppression." (PMID 32969187, 2020). "IL-4 and IL-10 are involved in inducing humoral immunity and they play a role in inducing IgG1 antibodies, which mediate complement-dependent cytotoxicity (CDC) and recruit effector cells for antibody-dependent cellular cytotoxicity (ADCC) as a promising antibody isotype for tumor immunotherapy." (PMID 32764343, 2020). "Similarly, there was an inverse relationship between tumor grade and IL-4 protein concentration in non-cancerous tissue in CRC (ρ = -0.55, p = 0.021)." (PMID 32512917, 2020).
tumor (continued). "Next, T cells that have successfully entered the tumor may be functionally repressed by immunosuppressive factors (like PD-L1 and CTLA-4), inhibitory cytokines (e.g., TGFβ, IL-4, and IL-10) and inhibitory cells (e.g., regulatory T cells and tumor-associated macrophages)." (PMID 32983080, 2020). "Th2 CD4+ T cells produce IL-4, IL-10, and TGF-β, which may boost tumor progression." (PMID 32595757, 2020). "The levels of IFN-γ, IL-2 and IL-4 did not correlate with tumor cells viability." (PMID 33312693, 2020). "As in the tumor tissues, IFNγ, IL-10, IL-17A, and IL-4 were measured and similar to tumor tissues, in vitro culture of T cells were found to have significantly increased levels of IFNγ and IL-17A, with G-CSFR−/− CD4+ T cells, while IL-10 and IL-4 levels were decreased compared to WT." (PMID 33042110, 2020). "Furthermore, release of Th2 cytokines, (i.e., IL-4 and IL-5) by basophils, mast cells and ILC2 may promote the recruitment of eosinophils and macrophages that control tumor progression." (PMID 33329534, 2020). "Furthermore, as cytokines can assist tumor progression, targeting IL-4, IL-13, IL-10, TGF-β, and CXCL5 or enhancing IFN-γ and some chemokines (e.g., CCL2, CCL3, CXCL9, CXCL10) may inhibit tumor invasion and metastasis." (PMID 32346605, 2020). "Likewise, IL-4 protein concentration in colonic non-cancerous tumor-adjacent tissue decreases along with increasing tumor grade." (PMID 32512917, 2020). "Contrary, M2 TAM are activated with transforming growth factor beta (TGF-β), interleukin 4(IL-4) and interleukin 13 (IL-13) to release a set of growth factors: VEGF, epidermal growth factor (EGF), and fibroblast growth factor (FGF); thus promoting angiogenesis and tumor growth." (PMID 30680411, 2019). "Furthermore, on day 23 of B16F10 cell injection, α-GalCer treatment increased the frequency of total NKT cells as well as IFN-γ-producing NKT cells whereas the frequency of IL-4 or IL-17A-producing NKT cells were not affected in the tumor (data not shown)." (PMID 31387637, 2019). "The expression of IL-4 in the NKT cells did not change between tumor and spleen (data not shown)." (PMID 31387637, 2019). "Hence, we hypothesized that transgenic expression of the 4/7ICR would serve not just to protect our CAR T cells from the inhibitory effects of IL4 (due to the ICR exodomain), but additionally promote their expansion at the tumor site." (PMID 29747685, 2018). "In addition, the mRNAlevels of IL-4, IL-10, and IL-13 were significantly higher in the tumor tissues whencompared to nontumor muscular tissues (Ps < .05)." (PMID 29950152, 2018). "For instance, work in a spontaneous mammary tumor model showed that IL-4/IL-13-activated TAMs, when exposed to tumor-derived colony-stimulating factor-1 (CSF-1), produce epidermal growth factor (EGF), which in turn promotes motility and intravasation of EGF receptor (EGFR)-expressing tumor cells." (PMID 30355585, 2018). "However, in our study, umbelliprenin increased levels of IFN-γ and decreased IL-4 both in tumor and non-tumor animals." (PMID 30127820, 2018). "Briefly, during the experiment, dCAR-T cells could release significant levels of cytokines only in the presence of cognate tumor cells expressing both CEA and MSLN, including 751 pg/mL IL-2, 9297 pg/mL IFNγ, 1777 pg/mL TNFα, 732 pg/mL IL-4, 8991 pg/mL IL-13, and 99 pg/mL IL-15." (PMID 30103775, 2018). "The CCR3+ tumor cells abundantly express IL-4 but not IFN-γ." (PMID 29915722, 2018). "On the other hand, these results indicate that tumor-derived oxysterols may shape the TME inducing a pro-tumor milieu, as confirmed by the detection in the TME of Mock-4T1 tumors of higher levels of the type-2 cytokine transcripts Il4, Il13, as well as the anti-inflammatory Il10 transcripts." (PMID 30333826, 2018).